CD4 (CD4 molecule)
Diseases named in the same sentence as CD4 in open-access papers (continued):
Sharing a sentence is not in itself a finding about the gene and the disease.
infection (continued). "ADCC was determined in infection experiments with wild-type (WT) or Nef- and Vpu-deficient (N-U-) virus, the latter exposing Env in the CD4-bound conformation at the cell surface." (PMID 31139189, 2019). "We have previously demonstrated in patients with AAV that the expansion of a subset of CD4 T cells that have lost expression of the costimulatory molecule CD28 (CD4+CD28null T cells) is independently associated with risk of infection and all-cause mortality." (PMID 30102389, 2019). "Despite the availability of a number of reports on opportunistic parasitoses among HD patients in Egypt, there is a paucity of data on the association of CD4+ counts with such infections." (PMID 31142275, 2019). "HIV-infected patients on suppressive cART are still a “fragile” population with an increased risk for acquiring IE, since subjects with CD4+ T-cells count > 500 cells/μL continue to be at risk of infection compared to patients with CD4 count > 750 cells/μL." (PMID 31382658, 2019). "In humans, many studies have described a CSP-specific CD4 T cell response that is associated with protection against natural infection and disease, and is able to inhibit pre-erythrocytic stage development." (PMID 31231377, 2019). "To eliminate the influence of abnormal CD4 T cell responses attributed to Tcf7 deficiency on CD8 T cell function during infection, we depleted CD4 T cells via injecting mice with the depleting antibody GK1.5 before LCMV infection." (PMID 30814995, 2019). "A decreased CD4/CD8 ratio has been shown by others to be associated with decreased host resistance to infection." (PMID 31443389, 2019). "Mechanistically, the study reveals that CD4 receptors and CCR5 co‐receptors of CD4+ T cells are significantly downregulated by arsenic trioxide treatment, which reduces susceptibility to infection after provirus reactivation." (PMID 31380187, 2019). "In fact, the dichotomic role of CD4+ T cells has been shown to be associated with the infection route." (PMID 31608035, 2019). "The study revealed that IL-1 contributes to the recruitment of CD4+ T cells to the site of infection and enhances IgM production, but also causes acute pulmonary inflammation." (PMID 30871179, 2019). "CD4+ cell counts < 200 cells/μl can be significantly associated with a higher infection rate with Cryptosporidium species, microsporidia and T. gondii among Egyptian HD patients." (PMID 31142275, 2019). "These CD4 +T cells were more susceptible than those of Ctrl to subsequent infection using two different R5-tropic viruses (YU2: Ctrl 1.15 ± 0.05% vs ECr/VCr 2.74 ± 1.11%; p=0.009; ADA: Ctrl 0.70 ± 0.04% vs ECr/VCr 1.79 ± 1.3%; p=0.008)." (PMID 30964004, 2019). "It is of interest that the macrophage-mediated HIV trans infection of autologous CD4+ T cells is associated with the control of disease progression." (PMID 30871222, 2019). "In another study, subtype D infection was associated with the fastest CD4 decline, compared to subtype A or C, in a Tanzanian cohort of pregnant mothers." (PMID 31795223, 2019). "Nevertheless, whatever the mechanism, the observed shift away from the structural antigens can be considered beneficial as it has been shown that CD4+ T-cell responses towards the structural antigens are associated with infection-enhancement." (PMID 31126293, 2019). "Other observations have shown that IFNAR blockade also inhibited TRAIL-induced apoptosis in CD4 T-cells during in vitro infection, and was associated with reduced frequencies of TRAIL+ and apoptotic cells in infected subjects." (PMID 31658294, 2019). "In mucosa, there is a large number of CD4+ T cells expressing the surface receptor CCR5, for which transmitted/founder viruses have the tropism; thus, the presence of CD4+ T cells in mucosa increases susceptibility to infection." (PMID 30787929, 2019).
infection (continued). "Infection of mice that lack CD4+ T cells either by antibody depletion or genetic deficiencies in CD4+ T cells and MHC class II resulted in a prolonged WNV infection in the CNS that culminated in uniform lethality by 50 days after infection." (PMID 31623175, 2019). "Dengue Virus-specific CD4+T cells responses are important in the control of infection and strong responses were previously associated with control of DENV infection in asymptomatic individuals." (PMID 31333679, 2019). "The CD4+ T-cell response shifted away from structural antigens previously associated with infection-enhancement." (PMID 31126293, 2019). "HIV-infected patients with CD4 cell counts >500 cells/μL had a higher risk of infections compared to those with a CD4 count >750 cells/μL." (PMID 31382658, 2019). "Our study revealed that CTX prophylaxis starting within 6 months after ART initiation was associated with a reduced incidence of TM infection in patients with a CD4+ cell count of <200 cells/μL." (PMID 31851879, 2019). "Overall, the increased production of CD4 TEff lymphocytes in CaV1.4-deficient mice was the most striking T cell subpopulation change compared to WT animals after MHV-68 infection." (PMID 31736943, 2019). "The combination of suboptimal amounts of VRC01 and Rh-α4β7 delayed infection, altered antiviral immune responses and minimized CD4+ T cell loss." (PMID 31083697, 2019). "This pattern was repeated on day 60 post-infection, (e.g., p < 0.0001 for global IL-4Rα−/− mice vs. CD4+ T cell-specific IL-4Rα-deficient mice)." (PMID 31475014, 2019). "The CD4+ T-cell response further shifted away from the structural antigens previously associated with infection-enhancement." (PMID 31126293, 2019). "In this work, we characterized the Sv129 mice as a new model of susceptibility to Leishmania amazonensis infection, during infection there was controlled IFN-γ production by CD4+ or CD8+ T cells and induced IL-17 production by γδ T cells." (PMID 31192210, 2019). "The best multivariable model for viral control included baseline CD4+ T-cell count, sex, subtype, age at the estimated date of infection, and HLA alleles B*45:01, B*57, and B*58:02." (PMID 30938435, 2019). "In the Ifnar1-/- mice the difference in mortality corresponded to a significant weight loss in CD4 depleted versus control animals and more severe clinical signs of disease during the course of infection." (PMID 30212537, 2018). "From the mouse studies, acute infection causes systemic activation of Natural killer (NK), CD4 and CD8 cells as well as the expected antibody response." (PMID 29330423, 2018). "Remarkably, the role of lamin A/C in viral clearance seems to be CD4+ T-cell dependent, since only CD4+ T-cells were adoptively transferred to T- and B-cell-deficient Rag1−/− mice before mouse infection with VACV." (PMID 29311549, 2018). "Here, we show a neutralizing antibody response, dependent on CD4+ T cells and IFNγ signaling, which we detected during the first week of infection and is associated with reduced viral load in the brain, prevention of rapid disease onset and survival." (PMID 30087337, 2018). "We have identified the ZIKV-encoded CD4+T cell epitopes which are targeted during infection and the cognate T cell receptors to these epitopes." (PMID 30212537, 2018). "The numbers of hair follicle-associated clusters, as well as the numbers of CD4+ T cells within each cluster, are increased following local infection and/or inflammation, indicating that tissue conditioning creates new dermal CD4+ T cell niches." (PMID 29904388, 2018). "Protection against infection is mainly associated with induction of parasite-specific T helper 1 (Th1) CD4+ T cells, and individuals with a healed but persistent primary cutaneous infection are protected against reinfection." (PMID 29922288, 2018). "Our results above show that the susceptibility to infection, the magnitude of inflammation and the number of CD4+Foxp3+ cells in the lungs are dependent on CCR4." (PMID 30584243, 2018).
infection (continued). "These envelopes showed ineffective binding to CD4 and the subsequent signaling activity to modify actin/tubulin cytoskeletons, which result in low fusion and deficient entry and infection capacities." (PMID 29636433, 2018). "The production of “large” phenotypes (greater cell and capsule size and giant cells) was associated with higher CD4 count and was negatively correlated with intracranial pressure indicators, suggesting that these are induced in early stage infection." (PMID 30352938, 2018). "The protective role of CD4 T cell responses has been documented for various pathogenic infections, including HIV." (PMID 29474461, 2018). "Similar to infectious bursal disease viruses (IBDV) infection, aflatoxicosis causes the changing of CD4+ and CD8+ lymphocytes infiltration." (PMID 30364039, 2018). "Several models of SIV infection have demonstrated infection of macrophages in several tissue compartments, including the spleen, lung, and brain, which is generally associated with a loss of CD4 T cells and accelerated disease progression." (PMID 29466439, 2018). "During the acute infection phase that typically lasts one to two months, the virus replicates rapidly and, by triggering multiple cell death pathways, causes loss of the CD4+ T-cells." (PMID 29510515, 2018). "The primary immunodeficiency of FIV, which is a gradual and progressive decline in CD4+ T lymphocytes, is a hallmark feature of both natural and experimental infection, and the most obvious fundamental feature to parallel HIV infection." (PMID 29677122, 2018). "Studies from human cohorts and nonhuman primates have shown, in a convincing way, that α4β7high memory CD4+ T cells are highly susceptible to infection." (PMID 29478152, 2018). "In many organs, DCs are considered essential for activation of autoreactive CD4+ T cells, particularly when DCs are activated by an inflammatory environment caused by infection or necrosis." (PMID 30524444, 2018). "Infectious challenge of IFNγ-treated CD4-depleted FVB mice with Pneumocystis demonstrated that they were highly susceptible to infection." (PMID 30283457, 2018). "Following virus transmission, acute/early phase of infection is characterized by a high-level peak of viremia, rapid loss of CD4+ T-cells in both peripheral blood and mucosal lymphoid tissues, and, in some cases, clinical symptoms." (PMID 29342870, 2018). "The low proportion of CD3+CD4+CD161+ T cells was significantly associated with a higher risk of infection before engraftment (cutoff of 3.72%, RR of 0.20, and P = 0.014) and CMV reactivation (cutoff of 3.72%, RR of 0.25, and P = 0.010)." (PMID 29511683, 2018). "Upon infection, the virus downregulates L-selectin expression through shedding, resulting in an apparent loss of central memory CD4+ T cells." (PMID 30026537, 2018). "Nevertheless, these natural hosts lack key features of pathogenic infection such as progressive CD4+ T cell loss, lymph node inflammation and fibrosis, gut barrier breakdown and microbial translocation, and chronic immune activation." (PMID 29659623, 2018). "Another important hallmark of T-cell exhaustion of CD8+ and CD4+ T-cells is the up-regulation of inhibitory molecules/negative immune checkpoints that bind to their cognate ligands expressed on APCs during infection with adenovirus, HIV, HBV and HCV." (PMID 30322028, 2018). "For instance, activated CD4 T cells are more susceptible to productive infection than their naïve counterparts." (PMID 29614779, 2018). "C. neoformans is the main source of infections in CM patients with CD4+ T-cell deficiency while C. gattii is a predominant species in the previously healthy." (PMID 29670625, 2018). "In 2008, BHIVA introduced specific guidelines recommending more HIV testing in populations at high risk of infection, and increased the CD4 count threshold at which they recommend PLHIV start ART." (PMID 29879977, 2018).
infection (continued). "It is established that patients with advanced HIV and low CD4+ T cell counts are susceptible to infection with MAC, and cases of disseminated MABS infection have been reported in these patients as well." (PMID 30443245, 2018). "Subsequently, it was demonstrated that HIV infection in humans leads to a similar loss of gut CD4+ T cells in the very early stages of infection." (PMID 29478152, 2018). "The phylodynamic model also included a high CD4 compartment (CD4 > 500) to assess risk during early infection." (PMID 30027754, 2018). "The Envs with the reverting I140T and V279A mutations showed an infectious activity below the anti-CD4 threshold and a nearly defective infection, whereas the reversing I400T mutation showed a limited but detectable infection activity." (PMID 29636433, 2018). "HIV-1 and SIVmac infections are characterized by a greater loss of CD4+ T cell subsets, such as Tcm, Tscm, and Th17, compared to SIVsmm and SIVagm infections." (PMID 29659623, 2018). "In vitro studies have shown that, in addition to limiting the amount of susceptible cells, Tregs can limit the infection of conventional CD4+ T cells through DC-CD4+ T cell immunological synapses." (PMID 29706961, 2018). "Considering that HIV-1 should overcome the cortical actin barrier during the early infection steps, the accomplishment of this process will predict the susceptibility of CD4+ T cells to infection." (PMID 29636433, 2018). "Here, we show that efficiency of MΦ-mediated HIV trans infection of CD4+ T cells is a unique characteristic associated with control of disease progression, and it is impaired in HIV-infected NP." (PMID 29643243, 2018). "We have longitudinally analyzed PD1 and Tim3 surrogate markers of T-cells exhaustion, in parallel with other markers of HIV progression, and its potential association with CD4 changes in treated and untreated infection." (PMID 29518102, 2018). "Definitive studies in mice and rats have shown that specific depletion of CD4+ T cells is sufficient to render these rodents susceptible to infection." (PMID 30283457, 2018). "An increase of CD8+ and double-positive CD4+CD8+ T cells associated with interferon-γ production are observed after day 10 post-infection." (PMID 29867849, 2018). "The subsequent chronic infection phase is marked by generalized immune activation and low levels of virus replication, but is accompanied by a sustained loss of CD4+ T-cells." (PMID 29510515, 2018). "Following infection of mice with cerebral malaria-causing P. berghei, both CD4+ and CD8+ T cells in the spleen exhibited increased BTLA expression." (PMID 30631323, 2018). "Collectively, these data suggest that increased antigen processing and presentation on MHC II molecules in infection-susceptible mice leads to exaggerated CD4+ T cell immune activation." (PMID 29339782, 2018). "Longstanding untreated infection is characterized by progressive loss of lymphocytes with a preferential decline in CD4+ cells, and consequently a decrease of CD4/CD8 ratios." (PMID 30352600, 2018). "The preferential infection of CD32+ cells in one donor (D2) was associated with significantly higher CD4 T-cell activation as measured by HLA-DR and CD69 expression, further indicating that CD32 expression is a marker of T-cell activation." (PMID 30013105, 2018). "Our previous study has reported that human Ad5-specific CD4 T cells induced by natural infection or rAd5 vaccination are more susceptible to HIV infection." (PMID 29474461, 2018). "In vivo, exogenous Nef and TNF secreted by infected cells as soluble proteins and/or as exosomes can activate uninfected CD4+ T cells and MDMs present in the vicinity and make them susceptible to infection." (PMID 29652795, 2018). "It is intriguing to find that γδ T cells can also work as APC to present pathogen infection-associated antigen to CD4+ and CD8+ T cells." (PMID 30116753, 2018).
infection (continued). "For mice deficient in CD4+ T cells, the survival rate of Flt3 ligand-treated mice was significantly higher than that of saline-treated mice (P < 0.05) by 51% after infection, at a rate comparable to those observed in immunocompetent mice." (PMID 30111869, 2018). "On the basis of flow cytometric analysis of CD4 T-helper subsets, an increasing Th17/Treg response over the course of the infection was most strongly associated with increased mortality (HR 4.41, 95% CI 1.69–11.5, p < 0.01)." (PMID 29695270, 2018). "In particular, we assume that all target cells are equally susceptible to infection, whereas evidence suggests that CD4+ T cells are more susceptible than CD8+ T cells in vitro, and memory lymphocytes are also preferentially targeted in vivo." (PMID 30592772, 2018). "Several studies have associated enteric viruses with more advanced HIV infection, suggesting that CD4 deficiency helps mediate enteric viral replication and infection." (PMID 30064366, 2018). "Selectively depletion of CD8+ T, CD4+ T, or B cells rendered 4-week-old A129 mice susceptible to the infection with PE243." (PMID 30087337, 2018). "This contrasts with permissive CD4 T cells (~5% of cells), in which infection causes the productively infected cell to undergo caspase-3 mediated apoptosis." (PMID 29614779, 2018). "PD-1 and PD-L1 deficient mice succumb to disease upon infection with Mtb due to unchecked expansion of CD4+ T cells." (PMID 30231065, 2018). "In contrast, the S. aureus induced an increase of the percentage of gated CD4 + IL-4 + T cells at days 7 and 14 post-infection in WT mice, which was reduced by ST2 deficiency." (PMID 29867945, 2018). "In particular, circulating CD3+CD4+CD161+ cell proportion was a risk factor for the occurrence of clinically or microbiologically documented infections before engraftment." (PMID 29511683, 2018). "Further, IFNγ-secreting CD4+ T cells were detected on day 6, day 10 and day 14 post infection (p.i.) using an enzyme linked immunospot assay (Elispot) under ex vivo stimulation with heat-inactivated HSV-1 (Heat-iHSV) for 24–48 hours." (PMID 30531962, 2018). "These high infection prevalences are found to be associated with a low CD4 counts and moreover, each of these infections is a risk factor for the other." (PMID 30080853, 2018). "In another pMHC class II system, SAXS was used to show the pathogen-derived proteins, Salp15 and gp120, caused binding-induced conformational changes in CD4 that subsequently influence CD4+ T cell activation during infection." (PMID 30581442, 2018). "It was largely accepted that while macrophages were capable of being infected by HIV, they were second to infection of CD4+ T cells, and possibly only targeted after significant loss of CD4+ T cells in the host." (PMID 29259605, 2017). "In multivariate analysis, CD4 nadir < 200 cells/μL was the factor associated with infection by HR-HPV (OR 3.66, 95% CI 1.05%–12.75%)." (PMID 28953633, 2017). "Monofunctional IL10 CD4 T cells were associated with high antigen burden and/or repeated infections, and were associated with protection from symptoms once infected." (PMID 29097996, 2017). "The impairment of peripheral CD4+ T cells adaptive responses in ALF can contribute to the susceptibility to infections seen in these patients." (PMID 28363639, 2017). "Unexpectedly, although, they exhibited a strong trend toward loss of CD4+ DC, emphasizing the sensitivity of this population to infection-induced loss." (PMID 28337202, 2017). "The weight loss of surviving animals of this group was less pronounced and peaked on day 16 post infection (-5.44±2.59%) while isotype-treated surviving CD4+IFNγ-/- T cell recipients still showed weight loss of -16.45±1.55% at this point in time." (PMID 28222146, 2017). "CD4+ T cell depletion prior to infection or early on during HBV infection resulted in loss of CD8+-dependent T-cell response whereas CD8+ T cell depletion during acute HBV resulted in failure of HBV clearance." (PMID 28450868, 2017).